DUSP6 (dual specificity phosphatase 6)
Diseases named in the same sentence as DUSP6 in open-access papers (continued):
Sharing a sentence is not in itself a finding about the gene and the disease.
glioblastoma (18 papers, 2012 to 2025). The most malignant astrocytic tumor (WHO grade IV). "Then, we examined the expression of mesenchymal markers associated with EMT in glioblastoma cultures, in naïve condition and in DUSP6-overexpression." (PMID 32771050, 2020). "Importantly, members of the DUSP protein family, including DUSP6, have recently been proposed as therapeutic targets for glioblastoma multiforme, where DUSP6 causes tumor-promoting effects and chemoresistance." (PMID 28423600, 2017). "DUSP6 is also known to be actively involved in oncogenesis showing unexpected tumor-promoting properties in human glioblastoma, contributing to the development and expression of the full malignant and invasive phenotype." (PMID 38769480, 2024). "This study was designed to explore DUSP6 involvement in epithelial-to-mesenchymal transition in glioblastoma." (PMID 32771050, 2020). "We previously showed that DUSP6 is upregulated in human glioblastoma and in vitro adenovirus-mediated overexpression results in a transformed phenotype." (PMID 32771050, 2020). "In accordance with our results, studies in glioblastoma also showed that DUSP6 overexpression increased resistance to cisplatin by regulating the ERK signaling pathway." (PMID 32231719, 2020). "The purpose of this study was to assess if DUSP6 activates epithelial-to-mesenchymal transition (EMT) in glioblastoma and its connection with the invasive capacity." (PMID 32771050, 2020). "Particularly, DUSP6 is upregulated in human glioblastoma where its overexpression induces reduction in proliferation rate." (PMID 32771050, 2020). "Dual specificity phosphatase-6 (DUSP6) is actively involved in oncogenesis showing unexpected tumor-promoting properties in human glioblastoma, contributing to the development and expression of the full malignant and invasive phenotype." (PMID 32771050, 2020). "Knockdown of TRIM11 significantly inhibited the transcription of DUSP6 in D-54 glioblastoma multiforme (GBM) cells." (PMID 31950060, 2019). "In glioblastoma, the overexpression of DUSP6 lessens tumor cell sensitivity to the anticancer DNA-damaging drug cisplatin." (PMID 24260056, 2013). "In non-small cell lung cancer, however, high DUSP6 levels have been found to predict poor prognosis, and evidence for a tumor-promoting role of DUSP6 in human glioblastoma has recently been provided." (PMID 22784513, 2012). "Indeed, DUSP6 mRNA and protein levels are upregulated in primary and long-term cultures of human glioblastoma cells (U251, T98G, and U87MG) compared to normal human astrocytes." (PMID 40943262, 2025). "Upregulation of DUSP6 has been reported to show a tumour-promoting role in human glioblastomas." (PMID 40943262, 2025). "Moreover, the inhibition of the catalytic activity of DUSP6 enhances the radiosensitivity of glioblastoma." (PMID 36982663, 2023). "Moreover, some previous studies have demonstrated that the depletion of DUSP6 activates ATM-CHECK2 pathway proteins and delays the DNA damage repair, and the inhibition of the DUSP6 catalytic activity can lead to radiosensitization in glioblastoma." (PMID 36982663, 2023). "By using qRT-PCR, we found high levels of mRNA DUSP6 across the glioblastoma samples." (PMID 32771050, 2020). "DUSP6/MKP-3 is upregulated in human glioblastoma cell lines." (PMID 26791049, 2016). "DUSP6 may have a potential role in radiotherapy because it regulates DNA damage responses, and inhibition of its catalytic activity leads to the radiosensitization of glioblastoma cells." (PMID 36982663, 2023). "The expressions of DUSP1, DUSP5, and DUSP6 were predominantly reported in pseudopalisading and perinecrotic regions of the GBM aggressive tumor, as reported in the Ivy Glioblastoma (GBM) Atlas Project (Ivy GAP) repository." (PMID 41158869, 2025). "While considering glioblastoma, we found SOX2, DUSP6, SLC24A3, KCNIP3, and DPP4 to be differentially the most upregulated, which have previously been found to be effective in glioblastoma formation and prognosis." (PMID 38769480, 2024).
glioblastoma (continued). "Surprisingly, mouse xenograft experiments showed that tumours arising from glioblastoma cells expressing DUSP6/MKP-3 grew significantly faster than non-expressing controls perhaps reflecting these changes in cell adhesion and morphology." (PMID 26791049, 2016). "DUSP6 is overexpressed in human glioblastoma, where it appears to cause cellular changes associated with invasion and metastasis and tumours derived from glioblastoma cells expressing DUSP6 grow significantly faster than non-expressing controls in mouse xenograft experiments." (PMID 35418690, 2022).
thyroid cancer (13 papers, 2015 to 2025). "We investigated the proliferative effect of DUSP5 and DUSP6 silencing in two BRAFV600E mutated human thyroid carcinoma cell lines (BCPAP and 8505c)." (PMID 28910386, 2017). "Targeted knockdown of DUSP6 by siRNA significantly inhibited the proliferation of human TPC1 thyroid cancer cells." (PMID 40575978, 2025). "Silencing of DUSP6 significantly decreases the cell viability and migration rate of FRO thyroid cancer cells 8, suggesting that DUSP6 plays a key role in malignant tumor metastasis." (PMID 41210685, 2025). "In thyroid cancer, increased DUSP5 and DUSP6 MAPK phosphatase expression was associated with higher ERK activity in BRAF-mutant tumors." (PMID 39436655, 2024). "For the gene DUSP6, a previous study showed that its gene expression increased in all of studied thyroid cancer cell lines, consistent with our results." (PMID 35267472, 2022). "Out of 28 protein-coding, five genes; TERT, FLT4, DUSP6, USP10 and POMC have already been implicated in thyroid cancer." (PMID 32324757, 2020). "For that purpose, we studied the MAPK pathway activation, the expression and regulation of DUSP5 and DUSP6, and the consequences of their inactivation in thyroid cancer cell lines." (PMID 28910386, 2017). "Silencing of DUSP5 or DUSP6 phosphatases by siRNA reduced the neoplastic properties of BRAFV600E-thyroid carcinoma cell lines." (PMID 28910386, 2017). "We found out that DUSP5 and DUSP6 are overexpressed in human thyroid carcinomas and are surrogate markers of MAPK pathway activation." (PMID 28910386, 2017). "Higher expression levels of the ERK1/2-specific cytoplasmic dual specificity phosphatase 6 (DUSP6) in comparison to benign and normal thyroid cells has been previously associated with PTC, especially with advanced thyroid carcinomas." (PMID 25922907, 2015). "In addition, hsa-mir-375 was inferred to be significant for patients’ survival with 34 associated ceRNAs, among which RUNX2, DUSP6 and SEMA3D are known oncogenes regulating cellular proliferation and differentiation in thyroid cancer." (PMID 29351231, 2018). "DUSP6 may have a pro-tumorigenic role in thyroid carcinogenesis, as recent data demonstrated that DUSP6 silencing reduced the neoplastic properties of human thyroid carcinoma cell lines with different genetic background (RET/PTC1 and BRAFV600E)." (PMID 28910386, 2017). "Furthermore we confirmed in our five BRAF-mutated human thyroid carcinoma cell lines that DUSP5 and DUSP6 induction was blocked by MEK inhibition, using a highly potent and selective MEK inhibitor namely AZD6244." (PMID 28910386, 2017). "The study demonstrates that DUSP6 and TSC22D1 are significantly upregulated in BRAFV600E mutant thyroid cancer and play an important role in the escape mechanism of tumor cells from OIS." (PMID 40650680, 2025). "Finally, DUSP5 and DUSP6 silencing reduced the cell migration and invasion capacities of two BRAFV600E thyroid cancer cell lines, thus suggesting a pro-tumorigenic role of these phosphatases in PTC." (PMID 28910386, 2017). "DUSP5 and DUSP6 have no tumor suppressor properties in two BRAFV600E thyroid carcinoma models, but instead they seem to have a protumorigenic role on thyroid carcinogenesis." (PMID 28910386, 2017).
gastric cancer (10 papers, 2010 to 2025). A primary or metastatic malignant neoplasm involving the stomach. "Knockdown DUSP6 with siRNA inhibited proliferation, migration, and invasion in gastric cancer cells." (PMID 40575978, 2025). "In contrast by the role of DUSP6 as a tumor suppressor that we describe here pharmacological inhibition of DUSP6, suppresses gastric cancer growth and metastasis and overcomes cisplatin resistance." (PMID 31027181, 2019). "In gastric cancer, DUSP6 inhibition can promote chemosensitivity, and it has also been characterized as a therapeutic target in acute lymphoblastic leukemia." (PMID 31164954, 2019). "Furthermore, inhibition of DUSP6 sensitizes gastric cancer cells to cisplatin-induced cell death and apoptosis in vitro and in vivo." (PMID 41210685, 2025). "Inhibition of DUSP6 by BCI suppresses proliferation, migration, and invasion and induces apoptosis in gastric cancer cells." (PMID 41210685, 2025). "The TRAPPC2L, DUSP6, MLH1 and RUNX3 genes more than 3-kb distal from the nearest retroelements were similarly overmethylated in the H. pylori positive mucosa (43%) and gastric cancers (LOH-B, 44%; LOH-L, 47%; LOH-H, 33%)." (PMID 21092120, 2010).
lung adenocarcinoma (10 papers, 2016 to 2025). A carcinoma that arises from the lung and is characterized by the presence of malignant glandular epithelial cells. "Analogous observations have been reported in RTK-RAS-mutant lung adenocarcinoma, where DUSP6 inhibition causes cell toxicity through ERK overdose." (PMID 35580987, 2022). "Importantly, in the GSE4537 dataset low DUSP6 expression showed to be associated with poor outcomes of lung adenocarcinoma, including decreased overall survival of the patients (long rank p = 0.0424)." (PMID 31027181, 2019). "Collectively, these results indicate that there is a positive correlation between OCT4 and DUSP6 expression in human primary lung adenocarcinoma specimens and NSCLC cell lines and that OCT4 overexpression enhances NSCLC cell migration and invasion." (PMID 41210685, 2025). "DUSP6 was upregulated in EGFR- or KRAS-mutant lung adenocarcinoma cells with high ERK phosphorylation levels, which enables tumor cell growth by suppressing hyperactive ERK." (PMID 34685488, 2021). "Here, we present results obtained from two different databases GSE4537 and LUAD TCGA indicating a good correlation between low DUSP6 expression and poor outcome of lung adenocarcinoma patients." (PMID 31027181, 2019). "Our findings are in agreement with those reported by Lee and colleagues who demonstrated a positive correlation between high DUSP6 expression and lung adenocarcinoma, because the majority of our case subjects (73.8%) had lung adenocarcinoma." (PMID 27418131, 2016). "Taken together, these biochemical and clinical studies strongly implicate the down regulation of DUSP6/MKP-3 as a driver of ERK-dependent resistance to TKI therapy in ELM4–ALK positive lung adenocarcinomas." (PMID 26791049, 2016). "Interestingly, targeting negative regulators of the RAS-RAF-MEK-ERK pathway, including DUSP6, leads to cellular toxicity in lung adenocarcinoma, further sustaining the possibility that CIC-deregulated tumors have common determinants." (PMID 36358827, 2022). "Moreover, DUSP6 levels and ERK activity were recently reported to be under translational control in KRAS-mutant lung adenocarcinomas." (PMID 39436655, 2024). "Low DUSP6 expression in lung adenocarcinoma patients diminishes survival but not in LUSC patients." (PMID 31027181, 2019).
Obesity (10 papers, 2015 to 2025). Accumulation of substantial excess body fat. "Nevertheless, after 26 weeks of high-fat diet exposure, we observed comparable body weight, fat and lean mass in DUSP6 WT and KO mice, suggesting overall normal susceptibility to develop obesity." (PMID 28873424, 2017). "DUSP6 deficiency was further linked with impaired adipocyte differentiation in vitro, and with decreased propensity for diet-induced obesity and pernicious sequelae in mice chronically exposed to HFD." (PMID 28873424, 2017). "Our data are in conflict to earlier reports that propose protection from diet-induced obesity and glucose intolerance in DUSP6 deficient mice." (PMID 28873424, 2017). "However, in a mouse model of obesity caused by a high-fat diet, DUSP6 exhibited the opposite effect." (PMID 36788275, 2023). "In this study, we initially investigated the DUSP6 gene effect on the porcine adipocyte adipogenesis to provide scientific clues for the improvement of pig meat quality and the treatment of obesity-related diseases." (PMID 40575978, 2025). "Obesity in mice increased the DUSP6 (MKP-3) protein content in the hypothalamus, this hypothalamic upregulation led to an increase of food intake, adiposity, and body weight." (PMID 40575978, 2025). "Enhanced ERK1/2 activity, achieved through deletion of its phosphatases DUSP6/8, leads to resistance to diet-induced obesity, improved glucose tolerance, and reduced serum triglycerides and lipid content in the liver and visceral adipose tissues." (PMID 40806659, 2025). "Our data stand in contrast to these earlier studies, displaying similar propensities for diet-induced obesity, as evidenced by similar fat mass, lean mass and body weight in DUSP6 WT and KO mice after 26 weeks of HFD exposure." (PMID 28873424, 2017). "We found unaltered Dusp6 mRNA levels in various brain areas of mice subjected to substantial metabolic challenges such as leptin injections, diet–induced obesity or prolonged fasting and refeeding." (PMID 28873424, 2017). "A subsequent report corroborated the resistance to diet-induced-obesity in DUSP6 KO mice and attributed this to an alteration of the gut microbiome, which conferred obesity protection by ameliorating the gut microbiota response to diet-mediated stress." (PMID 28873424, 2017). "Further exploration of the detailed mechanisms of DUSP6 in porcine adipogenesis should lead to the identification of additional targets for the selection of fat deposition traits in pigs and the prevention and treatment of obesity." (PMID 40575978, 2025). "Our data further indicate that DUSP6 deficiency does not alter the susceptibility of adult mice to develop diet-induced obesity." (PMID 28873424, 2017). "We furthermore aimed to assess in C57Bl/6J mice whether hypothalamic Dusp6 expression is regulated by diet-induced obesity or prolonged fasting and refeeding." (PMID 28873424, 2017). "In vivo, we assessed whether diet-induced obesity can alter Dusp6 expression in epididymal white adipose tissue (eWAT)." (PMID 28873424, 2017). "Similar propensities for diet-induced obesity in HFD-fed WT and DUSP6 KO mice were largely reflected by similar epididymal WAT gene expression levels of key enzymes involved in adipose tissue biology and function." (PMID 28873424, 2017). "In a previous report, DUSP6 KO mice exposed to HFD displayed decreased fat mass gain and lower propensity for diet-induced obesity." (PMID 28873424, 2017). "Mice lacking DUSP6/8 have enhanced resistance to diet-induced obesity, with the dramatically reduced serum TG, lipid content in the liver and visceral adipose tissues." (PMID 40575978, 2025). "Experiments utilising DUSP6−/− mice to study metabolism have now been performed with the finding that mice lacking DUSP6/MKP-3 are somewhat protected from diet-induced obesity." (PMID 30401534, 2019). "Notably, one DUSP in particular, DUSP6, regulates FGF signaling and is significantly increased in white adipose tissue during diet-induced obesity." (PMID 28580290, 2017).
Obesity (continued). "Mice lacking DUSP6/8 were resistant to high-fat diet-induced obesity." (PMID 40575978, 2025).
non-small cell lung carcinoma (9 papers, 2012 to 2025). A group of at least three distinct histological types of lung cancer, including non-small cell squamous cell carcinoma, adenocarcinoma, and large cell carcinoma. "All these data support the potential role of DUSP6 as a tumor suppressor gene in non-small cell lung cancer." (PMID 31027181, 2019). "Additionally, DUSP6 has been shown to be upregulated in non-small-cell lung carcinomas exhibiting hyperactive receptor tyrosine kinase activity and Ras/Raf signaling and potentially functioning as a negative-feedback regulator of mitogenic signaling." (PMID 25568665, 2014). "Similar results have also been documented in Non-small-cell lung carcinoma (NSCLC) cell lines, where the downregulation of DUSP6 resulted in increased ERK5 activation and epithelial–mesenchymal transition (EMT), which was reversed by inducing DUSP6 re-activation." (PMID 35053510, 2022).
depression (8 papers, 2017 to 2024). "DUSP6 overexpression also increased mRNA levels for the kappa opioid G-protein coupled receptor, which has been implicated in memory and depression, and additionally, OPRK1 promoter methylation that leads to reduced gene expression has been found to increase AD risk." (PMID 39006222, 2024). "Some genes, such as DUSP6 and mitogen-activated protein kinase genes, have been previously reported in the depression and suicide study while more novel genes were found." (PMID 36781900, 2023). "For example, downregulation of Dusp6, a female-specific hub gene in the major depressive disorder network, in the mouse prefrontal cortex mimics stress susceptibility in females, but not males, by increasing ERK signaling and pyramidal neuron excitability." (PMID 35241021, 2022). "DUSP6, as an important DEG, has been discovered to be associated with gonad development, altered sexual signs, and psychophysiological disorders, such as hypogonadism, absence of secondary sex characteristics, and mood and depressive disorders." (PMID 37026010, 2023).